FABP4 (fatty acid binding protein 4)
Diseases named in the same sentence as FABP4 in open-access papers (continued):
Sharing a sentence is not in itself a finding about the gene and the disease.
diabetes (continued). "However, FABP4 levels in both obese diabetes and obese non-diabetes subjects also differed significantly from non-obese subjects confirming the previously reported specificity of FABP4 as a biomarker of adipose tissue mass." (PMID 23119072, 2012). "In addition, FABP4 and FABP5 have been shown to be involved in the pathogenesis of various diseases including diabetes mellitus (DM), hypertension (HT), hyperlipidemia (HL), renal disease, heart diseases and malignant tumors." (PMID 39273233, 2024). "Serum FABP4 level of CVD subjects was significantly higher than healthy control (P = 0.001) and non-obese diabetes (P = 0.04) groups, but this difference was attributable to differences in BMI." (PMID 23119072, 2012).
metabolic syndrome (153 papers, 2009 to 2026). A cluster of metabolic risk factors for CARDIOVASCULAR DISEASES and TYPE 2 DIABETES MELLITUS. "Dysregulation of FABP4 has been linked to the development of metabolic syndrome and type 2 diabetes." (PMID 40090836, 2025). "Recent studies have demonstrated that FABP4 inhibitors or FABP4 deficiency can ameliorate lipid deposition and regulate dyslipidemia and lipotoxicity." (PMID 39198543, 2024). "As a result, FABP4 has been identified as a common risk factor and biomarker for adiposity and metaflammation in metabolic syndrome." (PMID 39028355, 2024). "In another previous study, it was demonstrated that FABP4 in peritumoral endothelial cells from human HCC samples with metabolic syndrome was overexpressed compared with those with other risk factors for chronic liver diseases." (PMID 37950277, 2023). "Elevated FABP4 has been observed in tumor-associated macrophages in neuroblastoma and hepatic stellate cells in hepatocellular carcinoma associated with metabolic syndrome." (PMID 37207357, 2023). "ROC curve showed that FABP4 was a poor diagnostic test to detect metabolic syndrome in vitiligo patients having 0.590 area under the curve (p = 0.34)." (PMID 34839983, 2022). "Other studies have shown that FABP4 is associated with kidney stone formation, and downregulation of FABP4 drives calcification, suggesting a link between kidney stones and metabolic syndrome." (PMID 36060264, 2022). "In fact, elevated serum concentrations of FABP4 are known to be associated with obesity, insulin resistance, hypertension (HT), dyslipidemia, atherosclerosis, renal dysfunction, purine metabolism, heart failure and cardiovascular events." (PMID 33503066, 2021). "FABP4 is mostly expressed in adipocytes and macrophages and is associated with several aspects of the metabolic and inflammatory pathway, such as metabolic syndrome and cardiovascular disease." (PMID 34987673, 2021). "FABP4 plasma levels are positively associated with BMI, waist circumference and metabolic syndrome, but also with inflammatory markers like CRP or IL-6 in type 2 diabetic subjects." (PMID 34638803, 2021). "Previous studies have established that FABP-4 was linked to type 2 DM, gestational DM, and metabolic syndrome." (PMID 34217172, 2021). "RBP4 and FABP4 are positively associated with metabolic syndrome, while APOD and LCN2 are ubiquitously expressed proteins with deleterious or beneficial effects, depending on their anatomical site of expression." (PMID 34638803, 2021). "Clinically, circulating FABP4 concentration, as a biomarker, can be associated with inflammation, metabolic syndrome, hypertension, and cardiovascular events." (PMID 33287461, 2020). "This is pertinent to the management of the metabolic syndrome in which FABP4 plays a causative role." (PMID 32856199, 2020). "Higher levels of FABP4 and lower levels of PPARγ in visceral adipose tissue, when compared with subcutaneous adipose tissue, suggest a causative link between FABP4 and the metabolic syndrome." (PMID 30857223, 2019). "Increased FABP4 levels are also linked to the early presence of metabolic syndrome components, as well as inflammation and oxidation markers in T2DM subjects." (PMID 30857223, 2019). "In human, some clinical evidences have implied the effects of adipsin, adiponectin and FABP4 from gut epithelial Paneth cells on colitis associated metabolic syndrome." (PMID 26687459, 2015). "Similar to FABP4, circulating FABP5 levels were detected at the level of about one tenth or less of FABP4 concentrations and were associated with metabolic syndrome components." (PMID 22121495, 2011). "On the other hand, suppression or loss of FABP4 function has been reported to exert protective effects against dyslipidemia, suggesting that elevated and deficient FABP4 levels may exert opposing effects on lipid metabolism." (PMID 39921359, 2025). "Plsama levels of FABP4 are associated with metabolic syndrome and CVD." (PMID 37794302, 2024).
metabolic syndrome (continued). "Serum FABP4 levels are predictive of the risk of metabolic syndrome." (PMID 37274820, 2023). "The role of FABP4 in the disease process of vitiligo could be mediated through associated dyslipidemia and hyperglycemia." (PMID 34839983, 2022). "FABP4 may play an active role in the disease process of vitiligo that could be mediated through associated dyslipidemia and hyperglycemia." (PMID 34839983, 2022). "Considering the potential relationship between FABP4 and preeclampsia, and its current evidence, we believe that FABP4 may be associated with different phenotypes of metabolic syndrome in pregnancy." (PMID 29394285, 2018). "Furthermore, in others prospective studies FABP4 levels are considered an early marker of metabolic risk for metabolic syndrome development and T2D." (PMID 23139800, 2012). "Therefore, the present study suggested that FABP4 may have an active role during the disease process of vitiligo that could be mediated through associated dyslipidemia and hyperglycemia." (PMID 34839983, 2022). "Thus, small molecules that inhibit the physiological function of FABP4 can mimic the phenotype of FABP4-deficient mice, and might be useful candidates for the treatment of metabolic syndromes." (PMID 31683588, 2019). "The regulation of FABP4, adipsin and adiponectin in gut epithelial Paneth cells by gut microbiota Lactobacillus may offer a clue to disclose the association between gut microbiota and metabolic syndrome." (PMID 26687459, 2015). "Paneth cells may produce FABP4, adipsin and adiponectin, which can regulate multiple physiological functions and are implicated in the pathogenesis of clinical entities, such as the metabolic syndrome in autocrine, paracrine and endocrine manners." (PMID 26687459, 2015). "This study is derived from the medical specialty thesis titled “The Association Between FABP4, Adiponectin, Irisin, and FSTL1 Levels and Metabolic Syndrome in Coronary Artery Disease” completed by Dr. Uyaner Kan under the supervision of Dr. Kilinc." (PMID 41187309, 2025). "This research highlights FABP4 and FSTL1 as significant biomarkers associated with CAD and metabolic syndrome, respectively, while reaffirming the roles of adiponectin and irisin in metabolic regulation." (PMID 41187309, 2025). "This study investigated the associations of circulating organokines (FABP4, FSTL1, adiponectin, and irisin) with CAD and metabolic syndrome in male patients undergoing elective coronary angiography." (PMID 41187309, 2025). "Increased levels of adipokine FABP4 are associated with several metabolic conditions and significantly higher levels are found in patients with HCC and metabolic syndrome compared to healthy individuals or those with HCV-related malignancy." (PMID 38927059, 2024). "In a German study, 1069 patients with previous coronary artery disease were followed for a duration of 10 years and circulating FABP4 levels increased as the number of metabolic syndrome components increased, and more so in females compared to males." (PMID 38698167, 2024). "It was demonstrated that HepG2 cells also express FABP4 when exposed to fatty acids such as oleic and palmitic acid (the free fatty acids found in high concentrations in the serum of metabolic syndrome patients)." (PMID 38927059, 2024). "FABP4 plays a role in developing metabolic syndrome through various pathways involving adipocytes and macrophages." (PMID 37794302, 2024). "Serum FABP4 level has been documented as a specific biomarker for metabolic syndromes and cardiovascular diseases." (PMID 37628833, 2023). "It has also been shown that high FABP-4 serum levels can be related to the prediction and diagnosis of obesity-related metabolic syndrome." (PMID 38024104, 2023). "Studies on FABPs revealed that the plasma levels of Fabp4 were elevated in metabolic syndrome patients and the Fabp1 null mice showed sex- and age-dependent weight gain as well as increased fat tissue mass." (PMID 35321016, 2022).
metabolic syndrome (continued). "Under pathological conditions, excessive or ectopic expression of FABP4 was demonstrated to play an important role in the incidence and progression of metabolic diseases, such as metabolic syndrome and T2D." (PMID 34174950, 2021). "Since serum FABP4 levels are correlated well with features of metabolic syndrome and are served as a predictor for the development of T2D." (PMID 34174950, 2021). "Recently, fatty acid binding protein 4 (FABP4), a cytosolic fatty acid chaperone, has been implicated in liver carcinogenesis related to the metabolic syndrome." (PMID 33198153, 2020). "FABP4 (adipose-FABP) have been described for their roles in the development of the metabolic syndrome through their mechanisms in adipocytes as well as macrophages." (PMID 33105856, 2020). "Studies conducted in FABP4 knockout mice have shown that this carrier protein has a crucial role in many aspects of the metabolic syndrome, with a potential role in future clinical treatments of this disorder." (PMID 31683588, 2019). "Adipocyte fatty acid–binding protein (FABP4) played critical roles in metabolic syndrome, inflammatory responses and cardiovascular diseases." (PMID 30969942, 2019). "An increased concentration of FABP4 was an independent biomarker of the development of metabolic syndrome in a five-year perspective in a Chinese population." (PMID 30857223, 2019). "FABP4 is thought to play roles in fatty acid transport and fat deposition in animals as well as in human metabolic syndrome." (PMID 29739312, 2018). "Circulating FABP4 is not only a potent biomarker but, as an adipokine, it also plays an important role in the development of metabolic syndrome and cardiovascular diseases." (PMID 30513800, 2018). "High concentration of FABP4 at baseline was an independent predictor for the development of metabolic syndrome during a five-year follow-up period in a Chinese population." (PMID 30513800, 2018). "The present study demonstrated for the first time that treatment with omega-3 fatty acid ethyl esters containing EPA and DHA for 4 weeks significantly decreased serum FABP4 concentration in patients with dyslipidemia." (PMID 26754658, 2016). "In this study, we investigated the effect of omega-3 fatty acid ethyl esters containing eicosapentaenoic acid (EPA) and docosahexaenoic acid (DHA) on serum FABP4 level in patients with dyslipidemia." (PMID 26754658, 2016). "Treatment with omega-3 fatty acid ethyl esters containing EPA and DHA decreases serum FABP4 concentration in patients with dyslipidemia, at least in part, via a direct reduction in expression and consecutive secretion of FABP4 in adipocytes." (PMID 26754658, 2016). "FABP4 has long been known to play a significant role in metabolic syndrome and the function of FABP4 in cardiovascular system has drawn increasing attention in recent years." (PMID 27294862, 2016). "Our studies suggest a new mechanism for systemic metabolism from gut microbiota, FABP4, adipsin and adiponectin in gut epithelial Paneth cells to metabolic syndrome." (PMID 26687459, 2015). "Fabp5 is expressed in many tissues including the liver and studies in mice null for both Fabp4 and Fabp5 demonstrate a role for Fabp5 in systemic glucose and lipid homeostasis as these mice are substantially protected from the metabolic syndrome." (PMID 24551121, 2014). "Fabp4 plasma concentration was also reported to be increased with the early presence of metabolic syndrome in humans." (PMID 23326526, 2013). "High serum levels of FABP4 at baseline independently predicted the development of metabolic syndrome during a 5-year follow-up period in a Chinese population." (PMID 22121495, 2011). "FabPs play roles in fatty acid uptake, transport and metabolism; FabPs expressed by adipocytes and macrophages (FabP4 and FabP5, respectively) play key roles in regulating systemic metabolism and are important mediators of metabolic syndromes in mice." (PMID 22216095, 2011).
metabolic syndrome (continued). "FABP4 has been proposed as a bridge between inflammatory processes and other biological pathways related to the metabolic syndrome." (PMID 20156355, 2010). "Omega‐3 fatty acids may reduce circulating FABP‐4 levels by suppressing its expression in adipocytes, as has been shown in a study of dyslipidemia patients." (PMID 40857027, 2026). "Serum FABP4 levels predicted the development of metabolic syndrome and type 2 diabetes." (PMID 39725654, 2024). "Importantly, these studies show that the onset of the metabolic syndrome occurs via expression of Fabp4 in adipocytes, while the initiation of atherosclerotic plaques occurs through Fabp4 expression in macrophages." (PMID 38698167, 2024). "At the same time, the physiological role of FABP4 in circulation is unknown but can be used as a biomarker for metabolic syndrome and CVD." (PMID 37794302, 2024). "As with metabolic syndrome–related disorders, numerous studies of a variety of cancers, in cultured cells as well as mouse models, have shown that pharmacologic or genetic inhibition of FABP4 diminishes cell proliferation, migration, and invasiveness." (PMID 37207357, 2023). "Furthermore, EPA or DHA treatment also decrease the serum FABP4 concentration in patients with dyslipidemia." (PMID 38085726, 2023). "Moreover, transcription factor FABP4 is sufficient to induce preadipocyte differentiation and is correlated with markers of metabolic syndrome and related disease." (PMID 34207778, 2021). "In the other studies serum FABP5 levels correlated positively with parameters of adiposity, adverse lipid profiles, serum insulin, adipocyte fatty acid binding proteins (A-FABP, FABP4), C-reactive protein levels and were higher in subjects with the metabolic syndrome (MS)." (PMID 34131888, 2021). "Circulating FABP4 is also considered as a marker of preclinical metabolic syndrome in humans." (PMID 33931964, 2021). "While their biological roles in blood remains unknown, serum FABP4 has been suggested as a potential biomarker for metabolic syndrome and CVDs." (PMID 33105856, 2020). "In our previous study, we hypothesized that increased circulating FABP4 concentrations could persist in GDM patients after delivery and might contribute to the increased risk of T2DM and metabolic syndrome for mothers with a history of GDM." (PMID 30818771, 2019). "aP2, also called fatty acid binding protein 4, is used as an early biomarker of metabolic syndrome." (PMID 31618980, 2019). "Many diseases are intimately related to FABP4/aP2 (e.g. metabolic syndrome and atherosclerosis and possibly osteoarthritis and FABP), but its involvement in SF in KOA is unknown." (PMID 30795769, 2019). "Based on our findings and previous studies, it appears that increased circulating FABP4 concentrations can persist in GDM patients after delivery and might contribute to the increased risk of T2DM and metabolic syndrome." (PMID 30857223, 2019). "On the basis of our findings and previous studies it appears that increased circulating FABP4 concentrations can persist in GDM patients after delivery and might contribute to the increased risk of T2DM and metabolic syndrome." (PMID 30513800, 2018). "More literature has shown that Fabp4 has an essential effect on the metabolic syndrome." (PMID 30519272, 2018). "Patients with metabolic syndrome had significantly increased FABP4 expression in epicardial fat." (PMID 27294862, 2016). "FABP4 mRNA expression in epicardial adipose tissue was recently reported to be profoundly increased compared with its expression in paraaortic adipose tissue in patients with metabolic syndrome." (PMID 25142635, 2014). "In conclusion, concentration of serum FABP4 may be not only a marker of metabolic syndrome that can be used even for ESRD patients but also a novel predictor of cardiovascular mortality in patients at high risk of atherosclerotic cardiovascular events." (PMID 22102888, 2011).